NKX2-4 (NK2 homeobox 4)
Description:
Probable transcription factor.
Synonyms: NKX2D; NKX2.4
Tractability: PROTAC: ubiquitination databases record sites on it.
Gene: Protein-coding gene on chromosome 20 (21,395,365 to 21,397,526, reverse strand). Ensembl gene ENSG00000125816.
Subcellular location: Nucleus
Subcellular location (Human Protein Atlas): Nuclear bodies
Gene Ontology:
Molecular function: protein binding; DNA-binding transcription factor activity, RNA polymerase II-specific; RNA polymerase II cis-regulatory region sequence-specific DNA binding; DNA binding; DNA-binding transcription factor activity; RNA polymerase II transcription regulatory region sequence-specific DNA binding
Biological process: cell differentiation; regulation of transcription by RNA polymerase II; animal organ development; positive regulation of transcription by RNA polymerase II; regulation of DNA-templated transcription
Cellular component: chromatin; nucleus
Genetic constraint (gnomAD): Loss-of-function variants: 6 observed, 2.42 expected, observed/expected ratio (o/e) 2.48. That is too few expected variants to judge how well the gene tolerates losing a copy. Missense variants: 601 observed, 344.67 expected, observed/expected ratio (o/e) 1.74, 90% interval 1.63 to 1.87. Synonymous variants: 299 observed, 169.03 expected, observed/expected ratio (o/e) 1.77, 90% interval 1.61 to 1.93.
Homologues: Orthologues: chimpanzee NKX2-4 (99% identical), macaque NKX2-4 (98% identical), pig NKX2-4 (95% identical), mouse Nkx2-4 (94% identical), dog NKX2-4 (94% identical), rat Nkx2-4 (94% identical), zebrafish nkx2.4a (66% identical), tropical clawed frog nkx2-4 (66% identical), zebrafish nkx2.4b (60% identical), Drosophila melanogaster scro (41% identical), Caenorhabditis elegans ceh-24 (29% identical), Caenorhabditis elegans ceh-28 (17% identical), and 4 more. Paralogues in human: NKX2-1 (58% identical), NKX2-2 (31% identical), NKX2-3 (29% identical), NKX2-6 (29% identical), NKX2-5 (29% identical), NKX2-8 (26% identical), NKX3-2 (20% identical), NKX1-1 (19% identical), NKX3-1 (18% identical), NKX1-2 (18% identical), NKX6-2 (15% identical), NKX6-1 (14% identical), and 1 more.
Diseases named in the same sentence as NKX2-4 in open-access papers:
NKX2-4 is named in the same sentence as 7 diseases in open-access papers, as found by Europe PMC text mining. Sharing a sentence is not in itself a finding about the gene and the disease. The quoted sentences say what the papers report.
acute myeloid leukemia (2 papers, 2021 to 2026). Acute myeloid leukemia (AML) is a group of neoplasms arising from precursor cells committed to the myeloid cell-line differentiation. "Here, we identify ectopic expression of NKL homeobox gene NKX2-4 in an erythroblastic acute myeloid leukemia (AML) cell line OCI-M2 and describe investigation of its activating factors and target genes." (PMID 34768865, 2021). "Erythroid acute myeloid leukemia (AML) cell line OCI-M2 expresses a particular oncogenic network: IRF6, in concert with ETV2 and HEY1, aberrantly activates NKL homeobox gene NKX2-4, which in turn represses megakaryocytic lineage factor FLI1." (PMID 41892358, 2026).
B-cell lymphoma (1 paper, 2021). "B-cell lymphoma cell line U-2932 expressed elevated NKX2-4 and reduced FLI1, suggesting that the repressive impact of NKX2-4 may play a role in malignant lymphoid cells as well." (PMID 34768865, 2021). "Additionally, B-cell lymphoma cell line U-2932 expressed elevated NKX2-4 levels as well." (PMID 34768865, 2021). "However, a potential role for overexpressed histone genes in aberrant NKX2-4 expression remained unclear, although we additionally detected elevated levels of ubiquitinated H2B in OCI-M2, which has been shown to impact NKL homeobox gene activity in B-cell lymphoma." (PMID 34768865, 2021).
erythroblastic leukemia (1 paper, 2021). "NKX2-4 is aberrantly expressed in erythroblastic leukemia cell line OCI-M2 and represses FLI1, while NKX2-3 is aberrantly expressed in megakaryoblastic leukemia cell line ELF-153 and activates FLI1." (PMID 34768865, 2021).
NKX2-4 also shares sentences with these, for which no sentence is quoted: acute erythroblastic leukemia (1 paper); autism (1); Cirrhosis (1); megakaryoblastic leukemia (1).